TLR7 (toll like receptor 7)
Diseases named in the same sentence as TLR7 in open-access papers (continued):
Sharing a sentence is not in itself a finding about the gene and the disease.
infection (continued). "In a mouse model of infection, TLR7/9 were required for optimal production of IFN-I and IFNγ, host survival, and restriction of cerebral fungal burden." (PMID 27459510, 2016). "We examined host cells at 7 dpi since this time corresponds to the peak IFN-1 production in lungs of wild-type mice and is also earlier than 10 dpi when TLR7/9-/- mice start to succumb to infection." (PMID 27459510, 2016). "Levels of TLR4 are increased by heat shock proteins and various cellular factors produced during infection, while the ligand for TLR7 is ssRNA, of which the H5N1 genome is comprised." (PMID 26238195, 2015). "Allergic Tlr7−/− mice displayed impaired IFN release upon RV1B infection, increased virus replication and exaggerated eosinophilic inflammation and airways hyper reactivity." (PMID 26108570, 2015). "Other studies have also reported this differential regulation of TLR3 and TLR7 following infection with a classical strain of IBDV." (PMID 25505077, 2015). "For instance, in the context of influenza virus infection of macrophages, activation of the inflammasome via TLR7 requires productive infection." (PMID 26295405, 2015). "To further demonstrate that MJWQH inhibited the NF-κB signaling pathway in the RNA level, we quantified the mRNA levels of TLR7, MyD88, and p65 in lung tissues on day 4 after infection." (PMID 26089947, 2015). "Positive signals are derived from RIG-I signalling in HIV infected cells that recognizes active, intracellular HIV infection and plasmacytoid dendritic cells via TLR7 signalling recognized infection." (PMID 26375588, 2015). "Wild-type and TLR7-deficient (Tlr7−/−) BALB/c mice were intranasally sensitised and challenged with HDM prior to infection with RV1B." (PMID 26108570, 2015). "As T. cruzi invades the host cell and reaches the phagolysosome environment, nucleic acid molecules from lysed parasites stimulate TLR7 and 9, leading to the production of Th1 proinflammatory cytokines important for controlling the infection." (PMID 26834737, 2015). "In the case of LCMV, viral RNA is likely a primary PAMP due to the inability of mice that lack TLR7, which recognizes ssRNA, to clear Cl13 infection." (PMID 25569216, 2015). "TLRs can sense the infection of RNA viruses, TLR7 binds with the ssRNA derived from viruses like influenza virus and TLR3 senses dsRNAs." (PMID 26206138, 2015). "In comparison to wild-type mice, the magnitude of γδ T cell expansion at day 3 post-infection was much lower in MyD88−/− and TLR7−/− mice (P<0.05 or P<0.01)." (PMID 25232836, 2014). "TLR7 is required for host protective immunity during wild-type or the attenuated WNV NS4B-P38G mutant infection." (PMID 25232836, 2014). "The magnitude of Vγ1+ T cell expansion in MyD88−/− or TLR7−/− mice was reduced at day 3 and remained lower in MyD88−/− mice at day 5 post-infection (P<0.05 or P<0.01)." (PMID 25232836, 2014). "The TLR3 levels peaked at 9 h after hMPV infection, and the levels of TLR4 and TLR7-9 peaked at 12 h after infection, then started to decline." (PMID 24039959, 2013). "Another study demonstrated that both duck and chicken TLR7 is only transiently expressed in peripheral blood mononuclear cells (PBMC) at the early stages of LPAIV H11N9 infection, followed by a decline as the infection progresses." (PMID 24016341, 2013). "The expression of MyD88, TLR9 and TLR7 (recently demonstrated as mediating the pDC response to LCMV) increased during LCMV-WE infection but only enabled infant pDCs to reach the levels observed at baseline in adult pDCs." (PMID 24376875, 2013). "Taken together, these results indicate that Heat-VAC infection of pDCs leads to the production of RNA species that are detected by the endosomal RNA sensing pathway mediated by TLR7/MyD88." (PMID 22606294, 2012). "Wt, TLR7 and AEP deficient lung epithelial cells, which are the first cells that will encounter IAV after infection, were purified and stimulated with imiquimod or IAV." (PMID 22916010, 2012).
infection (continued). "Upon infection with 1×105 PFU of MCMV, all WT and TLR7−/− male mice survived, while female WT and TLR7−/− mice were susceptible with survival rates, 58% and 45%, respectively." (PMID 23028824, 2012). "Although influenza virus induces IFN-α production through TLR7 activation the production of this cytokine following infection of PBMCs with the PR8 strain was comparable in males and females." (PMID 22768144, 2012). "In more recent studies, we determined that both DNA and RNA activate, respectively, TLR9 and TLR7 and are critical parasite components for induction of IL-12 and host resistance to a primary infection with T. cruzi." (PMID 22567144, 2012). "While B6 mice rapidly regained their pre-infection body weights, TLR7-/- mice maintained only 95% of their original body weight for the first week." (PMID 21966467, 2011). "In B lymphocytes, primary infection of EBV induces expression of TLR7 and downregulates expression of TLR9, as well as activates TLR7 signaling leading to expression of the downstream target IRF5 and cell proliferation." (PMID 21429244, 2011). "Taken together, these results suggest that TLR7 not only affects the accumulation of MDSCs at the site of infection, but can also modulate their ability to influence the subsequent T-cell response." (PMID 21966467, 2011). "Our results suggest that TLR7 and TLR8 variants have functional relevance in the setting of HCV-infection by conferring susceptibility to infection." (PMID 22022576, 2011). "Why TLR7/IRF-5 activation is only required at later stages of infection and what role it plays in various T-cell subsets are two more questions that remain yet to be answered." (PMID 21253574, 2011). "TLR7-/- MDSCs, when compared to B6, not only show increased recruitment to the site of infection and secrete increased amounts of Th1 inhibiting IL-10 in vivo, but also increase the amount of IL-4 production from OT-II T-cells." (PMID 21966467, 2011). "The data revealed that B cell-intrinsic Myd88 and TLR7 play a key role in the antibody response to infection, and that they regulate the development of germinal center B cells." (PMID 21998589, 2011). "In the present study we have demonstrated that the TLR7-mediated activation of IRF-5 is required for the development of host-protective Th1 responses to L. donovani at later stages of infection." (PMID 21253574, 2011). "Using mouse genetics, I have demonstrated that a host protein, Toll-like receptor seven (TLR7) recognizes retroviruses and regulates the antibody response to infection." (PMID 21998589, 2011). "Infection of TLR7-knockout mice revealed that both the IFNα response and lymphocyte activation were dependent on TLR7 signaling in vivo." (PMID 19568424, 2009). "Together, our data indicate that pDC's activated in a TLR7-dependent manner are primarily responsible for the rapid systemic IFNα response following infection of mice with LDV." (PMID 19568424, 2009). "Specific TLR7 inhibition, as achieved by DS-7011a might reduce these infection risks while providing therapeutic benefits for SLE." (PMID 40910948, 2026). "On the contrary, the inflammation-related genes, including TLR7, NF-κB, and INFα, as well as the key regulatory gene Caspase 3 involved in cell apoptosis, were markedly (p < 0.05) up-regulated following the GoAstV infection." (PMID 40071213, 2025). "Western blot results demonstrated that in IBV-infected CEK cells, baicalin significantly promoted the protein expression of IL-1β, IL-6, TNF-α, TLR7, and MyD88 at 24 h post-infection (hpi), whereas it markedly suppressed the expression of these factors at 48 hpi." (PMID 41375455, 2025). "The results revealed distinct temporal expression profiles of Toll-like receptors (TLRs), showing that TLR2, TLR4, TLR7 and TLR10 were significantly upregulated in a parabolic pattern, with TLR2 and TLR10 peaking at 36 h while TLR4 and TLR7 reached maximum expression at 24 h post-infection." (PMID 41305370, 2025).
infection (continued). "Based on these results, we can speculate that patients with mild disease, and to a lesser extent in patients with moderate disease, are able to induce TLR7 in early infection stages, which triggers the transcription of genes involved in the antiviral response." (PMID 41445728, 2025). "However, it is also possible that macrophages themselves, which express substantial amounts of TLR7, exhibit altered responses to direct infection depending on their sex of origin." (PMID 40143355, 2025). "Moreover, studies have demonstrated TLR7’s significant regulatory role in host infection by rabies virus, Newcastle disease virus, HIV, and others." (PMID 39973927, 2025). "Indeed, IAV-infected mice treated with the TLR7 antagonist IRS661 at 4 days post-infection (dpi) displayed reduced lung pathology and had improved survival." (PMID 39769461, 2024). "pDCs are resistant to infections by many viruses but engulf viral particles or material derived from infected cells and route these cargos to dedicated endosomes to trigger the TLR7/9-to-MYD88-to-IRF7 signaling pathway, which activates the promoters of all IFN-I/III genes." (PMID 38777879, 2024). "Moreover, while eosinophil populations in WT mice remained unchanged throughout the infection, TLR7 KO mice showed a significant increase in eosinophils in the lungs at 14 dpi." (PMID 39769461, 2024). "Biallelic expression of the TLR7/8 genes and, as a result, their increased activity in women may be one of the reasons for their relatively high resistance to infection." (PMID 39457048, 2024). "We postulated that the activation of TLR7 at the onset of infection can boost early antiviral IFN responses for protection against the virus while inhibiting TLR7 once an infection is established could suppress the cytokine storm and inflammatory lung damage." (PMID 39769461, 2024). "Skin explants have been used to investigate the effect of mosquito saliva and TLR7 agonists on ex vivo infection with Semliki Forest virus, cellular tropism of Zika virus, Zika virus transmission by DCs, and ex vivo infection with Mayaro virus." (PMID 38793609, 2024). "Myd88-KO and Tlr7-KO mice also exhibited a strong increase in infection-induced death." (PMID 38777879, 2024). "Given that Ly6Clo patrolling monocytes express high levels of TLR7, persistent TLR7 stimulation during infections with high viral load could perpetuate inflammation driven by the monocyte–neutrophil interaction." (PMID 39769461, 2024). "In contrast, 92.9% of mice vaccinated with TLR7-NP-adjuvanted HA fully recovered after infection." (PMID 36717665, 2023). "In addition, TLR7 escapes Chromosome-X inactivation, potentially leading to lower sensitivity of the TLR7 pathway in males prior to infection." (PMID 38045237, 2023). "This may be an indication of the greater infiltration of inflammatory cells to the lungs of TLR7 expressing mice following infection, consistent with enhanced airway infiltration." (PMID 37795093, 2023). "Histological analysis further demonstrated that TLR7-NP-adjuvanted HA vaccination could fully protect the mice from infection-induced pulmonary damage." (PMID 36717665, 2023). "As inflammation is a critical factor in stress erythropoiesis, the increased level of TLR7 expression in splenic CD45+ cells after the infection triggers our interest in studying the role of the innate immune response induced by TLR7 in extramedullary splenic erythropoiesis." (PMID 37180169, 2023). "Infection induced equivalent levels of IL-10 at 4 dpi in both genotypes, which then rose dramatically in WT mice at 7 dpi, but this increase was significantly less in TLR7 KO mice." (PMID 37795093, 2023). "To investigate if lung macrophages, which are part of the first line of respiratory pathogen defence, differed between the chicken lines, we determined innate immune gene expression in untreated birds and after stimulation with a TLR7 agonist (R848) and infection with H7N1 LPAI in vitro." (PMID 36992300, 2023).
infection (continued). "The expression of TLR7 in splenic CD45+ cells was increased after the infection." (PMID 37180169, 2023). "These diseases may have undiscovered impacts on the infection by HCV, which indirectly reflects in the association between the TLR7 gene polymorphism and the susceptibility to HCV, interfering with our judgment of the statistical analysis results." (PMID 37869679, 2023). "Although the detailed mechanisms underlying this specificity remain to be defined, the canonical role of TLR7 in sensing viral ssRNA makes it evolutionarily logical for the response to be specific to epithelial barriers, which must be breached for infection to be established." (PMID 37566453, 2023). "In accordance, blocking Tlr7 and Tlr9 signalling significantly reduced IL-6 in both wt and Ifitm3−/− cells to similar levels following infection with MCMV, suggesting that Ifitm3-mediated regulation of these responses restricts MCMV-induced cytokine production." (PMID 36075894, 2022). "Secondly, assuming that TLR7-signaling is restored in the latter phase of infection, why should reengaged signaling via TLR7 result in the observed pattern of the cytokine storm, which is skewed towards pro-inflammatory cytokines and chemokines with a systemic IFN response missing ?" (PMID 35065665, 2022). "The possible reason is that the activation of TLR7 signaling pathway may interact with other signaling pathways in different ways under normal and infection conditions, resulting in different effects of TLR7 on the differentiation and function of MDSCs." (PMID 36279265, 2022). "In the obese and elderly the establishment of TLR-tolerance prior to infection could explain the lower sensitivity of TLR7-signaling." (PMID 35065665, 2022). "In conclusion, infection with the NIBV SX9 strain activates the TLR7 signaling axis in target tissue, activates the nuclear transcription factors IRF7 and NF-κB, induces the production of proinflammatory cytokines, causes an inflammatory response and leads to kidney damage." (PMID 35402297, 2022). "TLR7 is expressed in immune cells, such as B cells, macrophages, and dendritic cells, recognizes single-stranded RNA of viruses and bacteria, and is involved in infection defense by inducing the production of interferon and inflammatory cytokines." (PMID 35744072, 2022). "Moreover, we found consistent responses to changes in the TLR7/NF-κB signaling axis, innate immune cytokines and histopathology throughout the course of infection." (PMID 35402297, 2022). "Thus, the theory predicted that defects in TLR7-signaling would confer an increased degree of vulnerability toward infection with SARS-CoV-2." (PMID 35065665, 2022). "However, in this study, the expression of TLR7 mRNA was somewhat different from that of M41 IBV in the later stage of infection, possibly due to the difference in the type of virus." (PMID 35402297, 2022). "Because a sublethal IAV load can paradoxically use the physiological inflammation mediated by TLR-7 pathway to enhance viral replication, it is possible that such infection in pregnancy can leverage these upregulated pathways, enhance viral replication, and worsen clinical outcomes." (PMID 35592667, 2022). "Moreover, it reveals that combined stimulation of newborn DCs via TLR7/8 and Mincle results in protection against infection with RSV by induction of antigen-specific Th1 cells, CD8+T cells, and neutralizing antibodies." (PMID 35918315, 2022). "Recently, TLR7 has been reported to be implicated in the sensing of SARS-CoV-2 infection, and the presence of TLR7-deficient genetic variants have been associated with a less-efficient control of the infection." (PMID 34576716, 2021). "Overall, exposure to PRRSV1 did not induce maturation of cDC1, cDC2, or CD14+ DCs, but modified TLR3 and TLR7-associated responses (except for cDC1), which may affect the development of adaptive immunity during PRRSV1 infection." (PMID 34177915, 2021).
infection (continued). "In the present study, we demonstrated that TLR7 activation by imiquimod could effectively inhibit the infection of primary macrophages by different strains of HIV." (PMID 34356516, 2021). "This might be induced by the amount of infection, recruiting lower TLR7-expressing lymphocytes, such as T cells and B cells, as we observed in mesenteric lymph nodes." (PMID 34692568, 2021). "In addition, a VirScan study of the serum samples of five index cases and three TLR7 hemizygous relatives revealed prior infection with diverse viruses." (PMID 34413140, 2021). "The percentages of TLR7+ cells in B lymphocytes also increased after infection." (PMID 34788282, 2021). "In summary, the administration of the combination of TLR7 agonist (GS-986) with N6-LS and PGT121 to macaques that initiated ART 14 days after SHIV-1157ipd3N4 infection was associated with a modest delay in viral rebound, despite limited dosing of bnAbs due to ADA." (PMID 33600506, 2021). "Moreover, the percentage and number of DCs in TLR7 KO mice at 6 weeks post infection significantly decreased compared to WT mice, and the percentage of IL-6-secreting DCs also decreased." (PMID 34692568, 2021). "Therefore, TLR7 KO mice that died within 6 weeks post infection were dissected, and the livers were sectioned." (PMID 34692568, 2021). "HSV-2 infected Tlr7-/- mice displayed local inflammation in the vagina, but infection did not cause hunching, hind/limb paralysis or lethality." (PMID 35058919, 2021). "The percentage of TLR7-expressing macrophages was also increased after infection." (PMID 34692568, 2021). "Here we examined the anti-HIV effect of imiquimod in primary human macrophages and demonstrated that TLR7 activation by imiquimod could effectively inhibit infection of the cells by different strains of HIV." (PMID 34356516, 2021). "One hypothesis is that chronic stimulation from RV in the upper airway initially induces high baseline interferon‐α levels, which blunts the response to further stimulation (e.g., TLR‐7 or prolonged infection)." (PMID 33236850, 2021). "Furthermore, the expression of TLR7 on B cells was dynamically detected from week 1 to week 7 after infection." (PMID 34788282, 2021). "In the context of IAV-infection, TLR7 and RIG-I are known to be activated." (PMID 32541772, 2020). "However, in the later stage of infection, TLR7 plays a pivotal role in the pathogenesis and disease advancement of HIV." (PMID 32858917, 2020). "We propose that infection-induced 5′-tRNA halves function as “immune activators” by being delivered to endosomes in surrounding cells via EV-mediated cell–cell communication and by activating TLR7." (PMID 33332353, 2020). "A key prediction of this hypothesis is that blocking TLR7 engagement during infection would mitigate disease progression or induce viral tolerance." (PMID 33202596, 2020). "TLR-7/9−/− (the double knockout mutant) or MyD88 mice made very little IFN-I in response to the yeast and mice lacking the IFN-γ receptor or TLR-7/9 were more susceptible to infection than controls as measured by survival and quantitative culture." (PMID 32545735, 2020). "Therefore, TLR7 seems to provide a dualistic function of preventing catastrophic effects of overwhelming infection in host cells while continuously preserving HIV replication in reservoir cells." (PMID 32858917, 2020). "Deletion of the TLR7 adaptor, MyD88, also resulted in higher levels of FV infection in knockout (KO) mice compared with heterozygous controls, up to at least 16 weeks post-infection, and MyD88 KO mice were unable to generate FV-specific IgG responses." (PMID 32751803, 2020). "Next, we investigated whether the effect of TLR7 on VSV dissemination was dependent on the site of infection." (PMID 30930901, 2019). "Notably, the mRNA levels of TLR7 were higher following infection of the virulent strain, as compared with the attenuated strain." (PMID 31514454, 2019).